SENP5 (SUMO specific peptidase 5)
Diseases named in the same sentence as SENP5 in open-access papers (continued):
Sharing a sentence is not in itself a finding about the gene and the disease.
tumor (10 papers, 2014 to 2025). "The tumor-specific role of SENP5 was validated through genetic knockdown and overexpression in a panel of tumor cell lines and tumor-derived organoids." (PMID 41268439, 2025). "Our experimental results confirmed that the overexpression of SENP5 significantly increased the sensitivity of tumor organoids to these four drugs in vitro." (PMID 41268439, 2025). "The results demonstrated that SENP5-overexpressing tumor organoids and cells exhibited markedly increased chemotherapeutic sensitivity even under severe hypoxia (1% oxygen)." (PMID 41268439, 2025). "Immunohistochemical analysis revealed that the expression of γ-H2AX was significantly elevated and the percentage of Ki67-positive cells was significantly decreased in SENP5 knockdown tumor cells after irradiation." (PMID 37684630, 2023). "Tumor growth was significantly inhibited in SENP5 knockdown cells combined with local irradiation, compared with single radiation groups." (PMID 37684630, 2023). "Our data showed that inhibiting SENP5 effectively suppressed organoids and tumor grow when combined with radiation." (PMID 37684630, 2023). "Our data showed that SENP5 knockdown combined with local irradiation significantly inhibited tumor growth (tumor volume)." (PMID 37684630, 2023). "Then the IHC staining in tissue array and quantitative analysis showed that SENP5 was significantly upregulated in the radioresistant tumors, which was further confirmed in tumor tissues through RT-PCR assay." (PMID 37684630, 2023). "Many HBV integration events occurred near or within fragile sites and other repetitive regions, such as TERT, FN1, MLL4, ROCK1, CCNE1, SENP5, Alu sequences, and microsatellites, which are prone to tumor development and progression." (PMID 28382278, 2017). "The first substrate of SENP5 identified was the tumor suppressor, PML, which has an essential role in the regulation of cell proliferation." (PMID 24926368, 2014). "We hypothesized that SENP5 overexpression might enhance the sensitivity of tumor cells to chemotherapeutic agents, a hypothesis that was validated by subsequent in vitro experiments." (PMID 41268439, 2025). "However, the extrapolation of our in vitro organoid findings, particularly regarding oxygen effects and SENP5-mediated sensitization, to the complex in vivo tumor microenvironment necessitates further validation in appropriate animal models." (PMID 41268439, 2025). "Further bioinformatic analysis revealed that SENP5 specifically activates the cell cycle, which may explain its role in driving tumor proliferation." (PMID 41268439, 2025). "Our findings revealed that both elevated and reduced expression levels of UBC9, SENP1, SENP3, SENP5, and SENP7 may be associated with poor prognosis across various tumor types." (PMID 41268439, 2025). "For the first time, we demonstrated that SENP5 overexpression can promote cell cycle progression in organoid models derived from four different tumors, thereby restoring sensitivity to chemotherapy in previously resistant tumor organoids." (PMID 41268439, 2025). "Notably, SENP5 exhibited tumor-specific overexpression, and functional assays indicate that targeting SENP5 inhibits tumor organoid growth with fewer off-target effects compared to UBC9 inhibition." (PMID 41268439, 2025). "Tumor weight in the SENP5 KD groups was also reduced, compared with the single radiation group." (PMID 37684630, 2023). "Consistent reduction in SENP5 knockdown cells derived tumors was observed in tumor size." (PMID 37684630, 2023). "A soft agar assay further assessed SENP5 involvement in tumor phenotype alterations." (PMID 24658161, 2014). "We indeed show that in two CDK6-dependent tumor cell models, depletion of SENP3 or SENP5 downregulates CDK6 and affects cell proliferation." (PMID 38065954, 2023). "The mRNA and protein levels of SENP5 were over-expressed in 10 pairs of HCC samples and demonstrated that SENP5 was required for the proliferation of HCC cells and tumour growth in vivo." (PMID 35331312, 2022).
tumor (continued). "It has been reported that the expression of SENP5 is elevated in OSCC and is related to the degree of tumor differentiation." (PMID 34267779, 2021). "Further subgroup analyses indicated that SAE1 and UBE2I had differential expressions with different stages, while SENP1, USPL1, SENP2, SENP5, SAE1, UBA2, and UBE2I had differential expressions with different tumor grades." (PMID 34267779, 2021). "Furthermore, we further stained Rad51 and p-CHK1 in tumor tissues of the CDX model, and observed the reduction of these two factors in tumors derived from SENP5 KD cells." (PMID 37684630, 2023). "Moreover, SENP1, USPL1, SENP2, SENP5, SAE1, UBA2, and UBE2I had differential expressions with different tumor grades." (PMID 34267779, 2021).
cancer (7 papers, 2014 to 2025). A tumor composed of atypical neoplastic, often pleomorphic cells that invade other tissues. "Bioinformatics analysis revealed that SENP5 is specifically expressed in certain tumors and is associated with overall survival in cancer patients, indicating its potential as a therapeutic target." (PMID 41268439, 2025). "Although SENP5 overexpression has little effect on normal progenitor cells, it promotes the proliferation of certain tumors, which conflicts with the goal of cancer therapy." (PMID 41268439, 2025). "The critical role of SENP5 in HR repair provides great opportunity for application in cancer therapy." (PMID 37684630, 2023). "SENP5 was also validated as a potent target for cancer therapy in patient-derived preclinical models." (PMID 37684630, 2023). "Elevated expressions of both SENP5 protein and mRNA were observed in cancer cells than normal cells." (PMID 37684630, 2023). "These SUMOylation regulators have lower overall average mutation frequencies in 33 types of cancer, although SENP1, SENP5, SENP7, and PIAS3 regulators have higher mutation frequencies." (PMID 33123273, 2020). "Other genes like CCNE1, SENP5, FN1, KMT2B, and DUX4 were alsoidentified by HGT-ID; these genes were previously reported to be associated with tumorigenesis or cancer invasion." (PMID 30016933, 2018). "As a result, we identified eight common mutated genes (EBAG9, MTDH, ATP6V1C1, OPA1, ATCL6A, BCL6, SENP5, KRAS) in the three different cancer types and used them as cross-cancer biomarkers to perform an integrative network analysis." (PMID 29459674, 2018). "Following our findings of SENP5 to be a unique prognosis biomarker, we analyzed its role as a factor in cancer phenotypes." (PMID 24658161, 2014). "Our findings revealed novel role of SENP5 in HR mediated DNA damage repair and cancer resistance, which could be applied as potent prognostic marker and intervention target for cancer radiotherapy." (PMID 37684630, 2023). "Through SUMO mass spectrometry analysis, we characterized H2AZ as a deSUMOylation substrate of SENP5, and depicted the SUMOylation balance of H2AZ in HR repair and cancer resistance." (PMID 37684630, 2023). "Our analysis of drug sensitivity using the Genomics of Drug Sensitivity in Cancer (GDSC) database revealed a potential correlation between SENP5 expression and sensitivity to 17-AAG, RDEA119, Trametinib, and Selumetinib, suggesting that these could be potential therapeutic agents targeting SENP5." (PMID 41268439, 2025).
bacterial infections (1 paper, 2022). "Comparison of these results with those obtained from bacterial infections showed genes associated with cell‐cycle progression and cell proliferation (RGCC, SENP5, SMC6, SERTAD3, MAD2L1BP) to be specifically upregulated in DC3s." (PMID 34333764, 2022).
SENP5 also shares sentences with these, for which no sentence is quoted: colorectal cancer (1 paper); endometrial cancer (1); ischemia reperfusion injury (1); kidney cancer (1); liver cancer (1); lung carcinoma (1); lung squamous cell carcinoma (1); non-small cell lung carcinoma (1); ovarian carcinoma (1); papillary thyroid carcinoma (1); undifferentiated thyroid carcinoma (1).